INS (insulin)
Diseases named in the same sentence as INS in open-access papers (continued):
Sharing a sentence is not in itself a finding about the gene and the disease.
Hypoglycemia (continued). "These autonomic shifts may amplify glucose uptake in skeletal muscle and alter hepatic glucose output, predisposing insulin-treated patients to post-coital hypoglycemia." (PMID 41030722, 2025). "However, after glucose intake, blood glucose gradually increased again, and a large amount of insulin injection at once carried the risk of hypoglycemia." (PMID 40955783, 2025). "The biological evaluation should include a hormonal profile to identify potential hormonal deficiencies that could justify hypoglycemia and insulin antibodies." (PMID 39941267, 2025). "Since tirzepatide enhances insulin secretion and suppresses glucagon, concurrent use with sulfonylureas or Insulin may increase the risk of hypoglycemia." (PMID 41405657, 2025). "In populations with limited access to blood glucose monitoring and healthcare support, strict glycaemic targets may increase the risk of hypoglycaemia, particularly among those using sulfonylureas or insulin." (PMID 41395632, 2025). "Notably, the patient was able to safely discontinue insulin and sulfonylurea therapy, reflecting improved insulin sensitivity and a lower risk of hypoglycemia." (PMID 40755669, 2025). "For example, NICE guideline NG28 states that CGM prescribing should be considered for a person with T2D on MDI therapy at risk of hypoglycaemia, which could be interpreted narrowly as intensive insulin therapy." (PMID 39676327, 2025). "But insulin can cause low blood sugar (hypoglycemia), which can be harmful." (PMID 41660655, 2025). "Insulin degludec has an onset of action within 1–2 h, lacks a distinct peak, and maintains glucose-lowering effects for up to 42 h, reducing the risk of hypoglycemia by 25% compared to insulin glargine and allowing greater dosing flexibility with timing variations of up to 8 hours." (PMID 41531706, 2025). "Regarding the BI components, insulin degludec has a longer duration of action and a flatter pharmacodynamic profile over the 24 h as compared with IGla‐10064 and is associated with a lower risk for nocturnal hypoglycaemia." (PMID 40678871, 2025). "Protocols that minimize glucose variability, such as structured insulin titration algorithms and threshold-based interventions, could reduce the risk of secondary brain injury while avoiding hypoglycemia." (PMID 40747311, 2025). "Across glucose ranges below 180 mg/dL, GLUCOSE consistently recommends lower average insulin doses than clinicians, reflecting a guideline-aligned strategy that prioritizes maintaining glucose between 140 and 180 mg/dL while reducing the risk for hypoglycemia." (PMID 40425725, 2025). "The reduction of hypoglycemia risk (66.9%) and dissatisfaction with prior therapies (55.8%) were also prominent factors, indicating that despite relatively preserved endogenous insulin production in T2DM, safety and convenience remain key drivers in treatment decisions." (PMID 41293743, 2025). "However, a history of DM complicates this control due to increased oxidative stress and protein glycosylation, decreased blood insulin levels following cardiac arrest, and the risk of hypoglycemia during the rewarming phase." (PMID 40725780, 2025). "On the contrary, several studies have reported that although continuous intravenous insulin infusion improves blood glucose levels more rapidly in critically ill patients, it is also associated with an increased risk of hypoglycemia and greater glycemic variability." (PMID 40400655, 2025). "Notably, hypoglycemia risk remains low for both formulations compared to insulin or sulfonylureas, reinforcing their suitability for patients prone to hypoglycemia." (PMID 40385819, 2025). "If U100 and U200 were to be confused in AID, this could lead to two-fold differences in the insulin dose delivered with the possibility of causing hypoglycemia, hyperglycemia, ketosis, or even diabetic ketoacidosis (DKA)." (PMID 41230085, 2025).
Hypoglycemia (continued). "Furthermore, the DBLG1 system automatically reduces the basal rate of insulin delivery for 16 h after Physical Activity mode is enabled to help mitigate the risk of post-exercise hypoglycaemia caused by increased insulin sensitivity." (PMID 39653802, 2025). "Insulin analogue as upgraded product of human insulin, is generally more expensive but more stable in controlling blood glucose and significantly reducing the risk of hypoglycemia." (PMID 40988682, 2025). "The risk of hypoglycemia is low when used as a monotherapy but may increase when combined with insulin or sulfonylureas." (PMID 40722655, 2025). "In insulin-treated patients, it has been speculated that recurrent hypoglycemia associated with neuronal cell death would be a cause, but the scientific evidence in support of this is meager." (PMID 39876043, 2025). "Despite the availability of various insulin regimens—including basal, bolus, and premixed formulations—clinical challenges persist, particularly in achieving glycemic targets while minimizing the risk of hypoglycemia." (PMID 41293743, 2025). "In fact, the combination of GLP-1 RA with basal insulin therapy causes a strong reduction in HbA1c and insulin dose reduction weight loss, and the combination of SGLT2i with insulin also effectively reduces HbA1c, insulin dose, and hypoglycemia and promotes weight loss." (PMID 41012462, 2025). "However in T1DM, MDI is associated with less time in range, higher HbA1c, and increased risk of hypoglycemia when compared with automated closed-loop insulin." (PMID 40746499, 2025). "However, insulin therapy increases hypoglycemia risk, which is associated with increased length of stay, morbidity, and mortality." (PMID 39816910, 2025). "However, sulfonylureas can cause weight gain and hypoglycaemia, while insulin or sulfonylureas have reduced the incidence of microvascular problems." (PMID 40574088, 2025). "Therefore, when the current BGL is less than 80, the insulin adjustment coefficient is set to 0, halting insulin infusion to reduce the risk of hypoglycemia." (PMID 39869550, 2025). "However, many glucose-lowering medications, particularly those that increase circulating insulin in a glucose-independent manner, can cause hypoglycemia." (PMID 40964167, 2025). "The double hit effect of IAA causing hypoglycaemia and erroneous insulin and C-peptide results would, with justification, confuse differential diagnosis, being clinically and biochemically capable of mimicking and masquerading as other pathologies and factitious hypoglycaemia." (PMID 41349642, 2025). "Furthermore, hypoglycemia associated with insulin use has been linked to increased mortality in these patients." (PMID 40463907, 2025). "Additionally, leveraging liver-specific promoters to achieve glucose-responsive transgene expression has minimized the risk of hypoglycemia while maintaining therapeutic insulin levels in T2D mouse models." (PMID 41226304, 2025). "Such tailored adaptations would not only enhance the model’s generalizability but also promote the widespread use of dynamic insulin titration protocols, ultimately improving patient outcomes by reducing dosing variability and mitigating hyper- and hypoglycemia risk." (PMID 40425725, 2025). "However, the newer agents can have an increased risk of hypoglycemia when used in combination with sulfonylureas and insulin." (PMID 40933374, 2025). "If this was experienced by a pilot of an aircraft, an unexpected additional bolus of insulin might cause hypoglycaemia and potential incapacitation." (PMID 39496965, 2025). "Recent studies infer that systemic glucose profiles are a crucial determinant of Ghrh neuromodulation of counterregulatory transmitter marker mRNA expression, as insulin (INS)-induced hypoglycemia (IIH) is associated with gain or loss of Ghrh control of distinctive marker gene profiles." (PMID 40534773, 2025).
Hypoglycemia (continued). "However, these IAA-insulin complexes then spontaneously dissociate, leading to increased free circulating insulin, which then causes late hypoglycemia." (PMID 40648766, 2025). "More severe, though less common, adverse reactions include risk of C-cell tumors, acute pancreatitis, cholelithiasis, hypoglycemia (especially while combined with insulin), elevated heart rate, renal impairment, hypersensitivity reactions, suicidal ideation, and behavior." (PMID 40565353, 2025). "Moreover, the greater risk for hypoglycaemia in CKD is acknowledged especially with the use of insulin or sulfonylureas/glinides as kidney function deteriorates." (PMID 39415639, 2025). "Additionally, hypoglycemia/insulin-induced copeptin elevation is associated with hypoglycemia awareness in T1D." (PMID 40428796, 2025). "Nevertheless, Linezolid may affect insulin sensitivity and increase the risk of hypoglycemia in patients." (PMID 40725154, 2025). "Furthermore, we observed an association between VPA and the occurrence of nocturnal hypoglycemia when the insulin dose equaled or exceeded 1.04 units per kilogram of body weight per day." (PMID 38954647, 2025). "The Canadian survey on self-reported hypoglycemia in patients living with T2D revealed that, due to the perceived risk of hypoglycemia, approximately a quarter of patients living with T2D intentionally miss, mistime, or reduce their basal insulin dose." (PMID 40110390, 2025). "Preserved β-cell function contributes to the improvement of insulin sensitivity, facilitates optimal glycemic control, and insulin dose reduction, and reduces the risk for hypoglycemia, ketoacidosis, retinopathy, nephropathy, hypertension, dyslipidemia, and CVD." (PMID 39998445, 2025). "Additionally, SGLT2 inhibitors resulted in a lower risk of hypoglycemia compared to agents such as sulfonylureas or insulin." (PMID 41012462, 2025). "This suggests that although mid-adolescents may experience improved glycemic control overall with morning PA, they could also face a higher risk of hypoglycemia, underscoring the need for vigilant glucose monitoring and individualized insulin/CHO adjustments." (PMID 41026404, 2025). "If such a decrease in plasma insulin were to occur during exercise in cool/cold water, this would be expected to oppose the glucose-lowering effect of exercise and thus decrease the risk of hypoglycaemia compared with exercise under warmer conditions." (PMID 40531210, 2025). "Notably, administering multiple doses of insulin carries the risk of inducing hypoglycaemia, which is a significant concern." (PMID 40836936, 2025). "In addition to exogenous insulin, physiologic insulin secretion by the patients’ β cells should contribute to the precise control of blood glucose concentration and reduce the risk of hypoglycemia." (PMID 39826690, 2025). "Third, insulin therapy is associated with the risk of hypoglycemia." (PMID 41464751, 2025). "In insulin naïve patients with very poor metabolic control, it allows to initiate an injection therapy with minimal risk of hypoglycemia and weight gain, thus overcoming the reluctance to therapy intensification of patients and diabetologists, and reducing clinical inertia." (PMID 39235480, 2025). "Particularly, the approach to managing diabetes - whether it involves insulin or oral hypoglycemic medications - affects the varying risks associated with hypoglycemia." (PMID 38706994, 2024). "However, all insulin-based regimens must be approached with caution due to the risk of hypoglycemia." (PMID 39744270, 2024). "There may also be a risk of hypoglycemia if a GLP-1 RA is used with insulin or insulin secretagogue medications." (PMID 38592214, 2024). "Furthermore, cultural and societal influences notably shape how medical information is interpreted, as evidenced by misconceptions about insulin-causing hypoglycaemia (FG1, P3) and certain dietary practises (FG3, P2)." (PMID 38491369, 2024).
Hypoglycemia (continued). "Consequently, patients with a high risk of hypoglycemia, especially those treated with insulin, should have their glycemic levels closely monitored." (PMID 39459449, 2024). "Inadequate dose adjustment and monitoring of insulin therapy may increase the risk of hypoglycemia and weight gain compared to OADs alone, potentially undermining insulin's benefits." (PMID 38969701, 2024). "Certain drugs, malicious administration of insulin, herbal supplements (fenugreek), alcohol, underlying eating disorders, liver disease, hypothyroidism, post-stomach resection, or end-stage renal disease are the causes attributed to fasting hypoglycemia." (PMID 39258039, 2024). "This strategy may be useful for not only discontinuing insulin, but also for decreasing SUs, and subsequent achievement of better glycemic control with minimizing the risk of hypoglycemia." (PMID 39430732, 2024). "Given previously reported direct effects of hypoxia on insulin action, we reasoned that rapid improvements in oxygenation following prone positioning may improve insulin sensitivity and increase risk of hypoglycaemia." (PMID 39532941, 2024). "Delayed peak insulin is a risk factor for preeclampsia and neonatal hypoglycemia during pregnancy." (PMID 39216124, 2024). "Studies have shown that the binding of insulin antibodies to exogenous insulin affects insulin reserves, leading to a massive dissociation of insulin that can result in excessive insulin levels in the blood, ultimately causing hypoglycemia." (PMID 39575003, 2024). "This safety feature makes sitagliptin a desirable option for glycemic control, particularly for patients who may have a high risk of hypoglycemia, such as the elderly or those on concurrent insulin therapy." (PMID 39768866, 2024). "Thus, insulin pumps are associated with lower risks of severe hypoglycaemia and diabetic ketoacidosis." (PMID 40302963, 2024). "In certain cases insulin regimens may need to be changed, for example from premixed to basal–bolus insulin because of an increased risk of hypoglycaemia." (PMID 38953925, 2024). "In addition to hypoglycemia, other common side effects associated with RAIAs often arise from inconsistencies in dosing frequency and the amount of insulin administered." (PMID 39457586, 2024). "In addition, the reduced P/T ratio of IGlar U100, when comparedto NPH, lowered the risk of nocturnal hypoglycemia, providing a tangible benefit andclinical advance in basal insulin replacement." (PMID 38224978, 2024). "In addition, once-weekly insulin was correlated with a higher risk of level 1 hypoglycemia (OR 1.42, 95% CI 1.26 to 1.6)." (PMID 39629047, 2024). "In dogs, IGla300 is reported to have lower potency compared with other insulin preparations, which typically results in a lower risk of hypoglycemia and may require higher therapeutic doses." (PMID 38831362, 2024). "In fact, even when taking into account that individuals using sulfonylurea, meglitinides, or insulin may target less stringent HbA1c levels because of risk of hypoglycemia, most individuals treated with oral polytherapy or with insulin had HbA1c levels > 7.0%." (PMID 38313340, 2024). "If these findings are both reproducible and translatable, it implies that insulin analogs protracted at the B1 position might result in a safer glucose-lowering profile that minimizes the risk of hypoglycemia." (PMID 39092439, 2024). "Smart nanocarrier-based drug delivery systems, such as glucose-responsive NPs synthesized from dextran, have demonstrated rapid and extended self-regulated insulin delivery, effectively reducing elevated blood glucose levels in mice and minimizing the risk of hypoglycemia." (PMID 39065795, 2024). "Notably, insulin therapy stands out as a primary and prevalent causative factor of hypoglycemia in diabetic patients." (PMID 39004753, 2024). "In addition, high doses of insulin are associated with the risk of hypoglycemia and provoke adverse cardiac events as well as further increases in body weight." (PMID 39274338, 2024).
Hypoglycemia (continued). "This case highlights two diagnostic pitfalls in diagnosing spontaneous hypoglycemia in adults: First, he was a healthcare provider, which raised the possibility that he could have likely taken exogenous insulin." (PMID 39119412, 2024). "While its ultra-fast action may pose a risk of hypoglycemia immediately following meals, it also reduces the risk of late postprandial hypoglycemia by better aligning insulin activity with glucose disposal." (PMID 39766270, 2024). "In the meta-analysis of safety outcomes, despite the higher risk for any adverse event observed with insulin icodec, the rates of serious adverse events and hypoglycemia episodes were comparable with those of control groups, indicating overall a noninferior safety profile." (PMID 38213906, 2024). "Depending on the relative extents of these 2 effects, a variant in the INSR gene could possibly result in decreased insulin clearance, leading to increased levels of endogenous circulating insulin postprandially and thereby be causative of hypoglycemia." (PMID 39659391, 2024). "However, switching a patient to an i.v. insulin infusion or multiple daily injections increases the risk of ketoacidosis and hypoglycaemia from potential miscalculations or delays in the initiation of an i.v. insulin infusion." (PMID 39099754, 2024). "Thus, few studies have analyzed risk factors other than insulin therapy for the occurrence of hypoglycemia during the treatment of hyperglycemic crises." (PMID 38594758, 2024). "Moreover, IDeg has been shown to be cost-effective in several economic models, particularly due to the reduced risk of hypoglycemia and lower overall insulin requirements." (PMID 39766270, 2024). "Other potential adverse reactions include hypersensitivity reactions, acute pancreatitis associated with discontinuation of metreleptin, hypoglycemia with concomitant use of insulin and other anti-diabetics, T-cell lymphoma, immunogenicity, and serious and severe infections." (PMID 38952397, 2024). "Augmented reality could show patients how much insulin to inject to avoid an accidental overdose that is a common cause of potentially fatal hypoglycaemia." (PMID 38193465, 2024). "In addition, pregnant women with type 1 DM are at a higher risk of experiencing insulin-induced hypoglycemia, which can be very dangerous for them." (PMID 38396408, 2024). "Authors caution that insulin-induced moderate hypoglycemia might increase the risk of substrate deficiency and potential subsequent energy depletion during HI brain injury." (PMID 38235171, 2024). "A previous pharmacist-led intervention showed that sulfonylurea and/or insulin could be de-intensified in 18% of the patients with high hypoglycaemia risk, which is more than double the percentage observed in our study." (PMID 39407915, 2024). "Although no randomized controlled trial has compared IGlar with NPH insulin in Thailand, the risk reduction of severe hypoglycemia by IGlar compared with NPH insulin was based on the results of a meta-analysis of randomized controlled trials, which is classified as the highest level of evidence." (PMID 39877917, 2024). "Finally, the iatrogenic causes of hypoglycemia include the administration of drugs like insulin and sulfonylurea." (PMID 39595353, 2024). "Moreover, perioperative fasting and insulin therapy can increase the risk of hypoglycemia, which is particularly concerning because sedation and anesthesia obscure the typical signs of hypoglycemia." (PMID 39458119, 2024). "Unlike systemic insulin administration, which may be associated with hypoglycemia risk, topical application allows for localized delivery of insulin to the wound site, minimizing systemic side effects." (PMID 38731363, 2024). "Implementing adjusted management based on patients’ characteristics and the intensive monitoring of blood glucose levels for patients at risk after the administration of insulin could help address the issue of hypoglycemia following hyperkalemia treatment." (PMID 39274318, 2024).